USH2A (usherin)
Diseases named in the same sentence as USH2A in open-access papers (continued):
Sharing a sentence is not in itself a finding about the gene and the disease.
retinitis pigmentosa (89 papers, 2010 to 2025). Retinitis pigmentosa (RP) is an inherited retinal dystrophy leading to progressive loss of the photoreceptors and retinal pigment epithelium and resulting in blindness usually after several decades. "USH2A, a protein-encoding gene primarily implicated in Usher syndrome type IIa and retinitis pigmentosa, was previously associated with poor prognosis in colon adenocarcinoma." (PMID 40312292, 2025). "The target of choice is Usherin (USH2A) whose mutations are associated with severe forms of Retinitis pigmentosa." (PMID 40777850, 2025). "Biallelic variants in USH2A are associated with retinitis pigmentosa (RP) and Type 2 Usher Syndrome (USH2), leading to impaired vision and, additionally, hearing loss in the latter." (PMID 39120292, 2024). "Pathogenic variants in the USH2A gene account for over half of the syndromic cases of retinitis pigmentosa." (PMID 39596236, 2024). "These USH2A mutations are associated with congenital moderate-to-severe hearing loss, pre-to-post pubescent onset retinitis pigmentosa (RP), and unaffected vestibular function." (PMID 36810733, 2023). "Among the cone-rod dystrophy patients, ABCA4 was the most common mutated gene, meanwhile, USH2A was the most prevalent among the retinitis pigmentosa patients." (PMID 34327195, 2021). "USH2A mutations are associated with Usher syndrome type IIa, retinitis pigmentosa, and tongue squamous cell carcinoma." (PMID 34795697, 2021). "USH2A is a common causal gene of retinitis pigmentosa (RP), a progressive blinding disease due to retinal degeneration." (PMID 33105608, 2020). "In particular, all the Usher patients (i.e., patients displaying HL and retinitis pigmentosa) were molecularly characterized, identifying homozygous or compound heterozygous mutations in USH2A and MYO7A genes." (PMID 33105617, 2020). "Bilallelic variants in the USH2A gene can cause Usher syndrome type 2 and non-syndromic retinitis pigmentosa." (PMID 33121974, 2020). "The mutations in the USH2A genes are responsible for 5∼10% of the cases with retinitis pigmentosa and 60∼90% of the cases with Usher syndrome type II." (PMID 30245926, 2018). "In the present study, we confirm that recessive variants affecting USH2A function are a common cause of retinitis pigmentosa with disease-causing variants being spread throughout the gene." (PMID 25649381, 2015). "USH2 mutations result in an autosomal recessive disorder characterized by retinitis pigmentosa and mild-to-moderate sensorineural hearing loss, and the USH2A gene is most commonly mutated." (PMID 25388789, 2014). "Van Wijk and colleagues showed that a protein domain-based skipping of (multiple) exons, based on a powerful combination of 3D bioinformatic modeling with in vitro and in vivo models, is a highly promising treatment paradigm for retinitis pigmentosa caused by pathogenic variants in the USH2A gene." (PMID 37313440, 2023). "Finally, the recognition of biallelic pathogenic USH2A mutations in this STGD patient raises the need for frequent ophthalmological examinations for a potential early identification of retinitis pigmentosa manifestations." (PMID 36051698, 2022). "Splice-switching AONs have already made a mark in the field of therapies for IRD with ongoing clinical trials for Leber congenital amaurosis due to a deep-intronic mutation in CEP290 c.2991+1655A>G and retinitis pigmentosa caused by coding variants in exon 13 of USH2A." (PMID 36552712, 2022). "Mutations within Ush2a are the most common cause of retinitis pigmentosa and Usher syndrome type 2." (PMID 34717547, 2021). "For retinitis pigmentosa, variants of USH2A and EYS were the most common causative gene mutations." (PMID 33691693, 2021). "As one example, retinitis pigmentosa-39 (RP39) is caused by homozygous or compound mutations in USH2A gene, which encodes protein Usherin, required for photoreceptor (also hair cells in the cochlea) maintenance because of its role in cilia formation and function." (PMID 33132839, 2020).
retinitis pigmentosa (continued). "As retinitis pigmentosa may develop after puberty for patients with USH2A mutations, we recommended that visual acuity and visual fields of the patient be monitored by an ophthalmologist at older age." (PMID 31992338, 2020). "Mutation in USH2A gene is observed in patients with Usher syndrome type II or non-syndromic retinitis pigmentosa, however its function is yet unknown in cancer." (PMID 32626534, 2020). "Mutations in USH2A can also cause retinitis pigmentosa on its own." (PMID 23991284, 2013). "In particular, USH2A variants displayed genotype-phenotype segregation (e.g., allelic hierarchy) 34: functional null alleles were associated with earlier, severe hearing loss, while two hypomorph alleles in trans often caused delayed, progressive hearing loss with retinitis pigmentosa." (PMID 40592345, 2025). "Reported here is a rare case of optic nerve coloboma in a patient found to have USH2A-related nonsyndromic retinitis pigmentosa upon genetic testing." (PMID 40225234, 2025). "This study compares clinical characteristics of retinitis pigmentosa (RP) associated with mutations in the EYS and USH2A genes in a Southeast Asian cohort." (PMID 39932467, 2025). "Affecting approximately 1 in 4000 individuals worldwide, retinitis pigmentosa exhibits significant genetic heterogeneity, with mutations in genes such as RHO, PRPF31, RPE65, USH2A, and NR2E3, which contribute to its diverse clinical presentation." (PMID 40869487, 2025). "Biallelic variants in USH2A are associated with both Usher Syndrome Type 2 (USH2), characterised by hearing loss followed by retinitis pigmentosa (RP), as well as non-syndromic RP (nsRP)." (PMID 39120292, 2024). "Of particular interest in the protein modeling was that of usherin (USH2A), the known retinitis pigmentosa gene." (PMID 36596879, 2023). "Here, the authors show in a mouse model of this disease that the expression of mutant usherin leads to retinitis pigmentosa and structural defects in the photoreceptor cilium associated with mislocalization of VLGR1 and WHRN." (PMID 36810733, 2023). "For example, one participant identified as a carrier for USH2A gene had a family history of retinitis pigmentosa in her offspring." (PMID 35488281, 2022). "Mutation in the USH2A gene is the most common cause of inherited retinal dystrophy (IRD), including non-syndromic retinitis pigmentosa (RP) and Usher syndrome II (USH2)." (PMID 36034145, 2022). "After evaluating with this test, 16 known variants were detected in 16 individuals in whom four showed retinitis pigmentosa (RP) and hearing loss with homozygous and compound heterozygous variants in MYO7A, CDH23 and USH2A genes." (PMID 31850270, 2019). "Four patients had retinitis pigmentosa (RP) with HL in three causative genes, MYO7A, CDH23 and USH2A, with novel and known variants." (PMID 31850270, 2019). "Mutations in MYO7A, USH1C, CDH23, PCDH15 and WHRN have also been reported in patients affected by hearing impairment only, while USH2A is also involved in isolated retinitis pigmentosa." (PMID 21569298, 2011). "Patients with Usher syndrome II due to autosomal recessive USH2A variants typically present with moderate-to-severe nonprogressive congenital sensorineural deafness and develop retinitis pigmentosa in the first to second decade of life." (PMID 40225234, 2025). "Retinitis pigmentosa was the most represented phenotype (56%), followed by cone dystrophy (11%) and Leber congenital amaurosis (7%), while ABCA4 was the most frequently mutated gene (18%), followed by USH2A (9%) and RPGR (5%)." (PMID 35836572, 2022). "In addition to HL, the proband from Family 30 also suffers from retinitis pigmentosa, and genetic testing identified a homozygous deletion encompassing exons 22–24 of the USH2A gene." (PMID 35682719, 2022). "Pathogenic mutations in USH2A are a leading cause of visual loss secondary to non-syndromic or Usher syndrome-associated retinitis pigmentosa (RP)." (PMID 35457016, 2022).
retinitis pigmentosa (continued). "Four families (8, 10, 23 and 53) showed different compound heterozygous mutations of USH2A, and the mutations were associated with the nonsyndromic retinitis pigmentosa of these patients but without obvious hearing impairment." (PMID 33781268, 2021). "USH2A variants are the most common cause of Usher syndrome type 2, characterized by congenital sensorineural hearing loss and retinitis pigmentosa (RP), and also contribute to autosomal recessive non-syndromic RP." (PMID 31998945, 2020). "USH2A mutation is the most common cause of retinitis pigmentosa, with or without hearing impairment." (PMID 31766479, 2019). "Lack of ophthalmologic abnormal finding from SHJ37 carrying USH2A variants does not rule out a possibility of USH2 since retinitis pigmentosa can develop later." (PMID 25373420, 2014). "Second, they demonstrate that USH2A mutations cause retinitis pigmentosa by affecting photoreceptors later in life rather than by altering their development." (PMID 23991284, 2013). "Mutation of USH2A can cause retinitis pigmentosa with or without sensorineural hearing loss." (PMID 33781268, 2021). "In our study, interestingly, the proband (II:2) and her affected older brother (II:3) in pedigree 1 were found to be heterozygous carriers of M1 and M2 mutations (on the same chromatid) in the USH2A gene, associated with retinitis pigmentosa without hearing loss." (PMID 32893482, 2020). "Their studies indicated that mutations in USH2A may cause retinitis pigmentosa without hearing loss." (PMID 20309401, 2010). "The resulting dendrogram captures some of the known phenotypic similarities in IRDs such as Stargardt phenocopy genes (ABCA4, PRHP2 and PROM1), retinitis pigmentosa genes (RPGR and USH2A) and achromatopsia genes (CNGA3 and CNGB3)." (PMID 40567353, 2025). "On the other hand, in a female patient with non-syndromic retinitis pigmentosa, a paternal UPD for the telomeric region of chromosome 1, including the USH2A gene, was demonstrated." (PMID 36051698, 2022). "Moreover, multiple cases of various retinitis pigmentosa types were reported to be a result of alterations in other genes and uniparental isodisomy on chromosome 1: in the ABCA4 gene, in the USH2A gene, and in the CRB1 gene." (PMID 38002999, 2023). "Mutations in USH2A are linked to Usher syndrome type II (USH II) and non-syndromic retinitis pigmentosa (RP)." (PMID 31904091, 2020). "However, younger patients (aged < 16 years) did not exhibit overt retinitis pigmentosa even when they had biallelic truncated alleles, suggesting that USH2A-related USH2 can mimic nonsyndromic hearing loss." (PMID 37981655, 2023). "For example, although the proportion of cochlear hair cell Ush2a C230072F16Rik did not diminish with ARHL, mutations in its marker gene USH2A causes Usher syndrome type IIa, an autosomal recessive disorder characterized by moderate to severe sensorineural hearing loss and retinitis pigmentosa." (PMID 38094513, 2023).
hearing loss (58 papers, 2009 to 2026). "USH2A, ADGRV1, and WHRN are the three known USH2 causative genes, which are also linked to isolated retinal degeneration and hearing loss." (PMID 41654259, 2026). "CERKL (Ceramide Kinase Like) mutations are associated with autosomal recessive RP and cone–rod dystrophy, while USH2A (Usherin) mutations cause both nonsyndromic RP and Usher syndrome type 2, which combines RP with hearing loss." (PMID 41562913, 2026). "Generally, pathogenic variants in USH2A are linked to the classic USH II profile: moderate-to-severe hearing loss with RP emerging during adolescence or early adulthood." (PMID 40149483, 2025). "A prior study showed that patients carrying two truncation mutations in USH2A have a younger onset age and faster progression of hearing impairment and vision loss compared to those with one or two alleles encoding missense mutations." (PMID 40677926, 2025). "Biallelic LOF variants in USH2A typically cause USH2 with congenital or early-childhood-onset hearing loss." (PMID 39120292, 2024). "The USH2A gene exhibits an allelic hierarchy; there are tissue-specific genotype–phenotype correlations for various clinical manifestations of USH2A-related disorders, including hearing loss, RP, and olfactory function." (PMID 37981655, 2023). "The current study aimed to identify pathogenic variants in a Chinese patient with hearing loss and to report the identification of a novel p.(Phe1583Leufs*10) variant in USH2A, which met the needs of prenatal diagnosis of the patient's mother." (PMID 34376197, 2021). "The results of the present study identified two compound heterozygous USH2A variants in a patient with hearing loss and reported a novel USH2A variant which expands the spectrum of USH2A variants in USH." (PMID 34376197, 2021). "In this study, only three causative genes, MYO7A, CDH23 and USH2A with novel and known variants contributed to both RP and hearing loss." (PMID 31850270, 2019). "It is likely that severe disruption of USH2A causes both hearing and RP phenotypes in most cases, while milder disruptions to USH2A only cause RP except in patients with a background or environment predisposed to hearing loss." (PMID 26338283, 2015). "Known pathogenic variants in MYO15A, GJB2, and USH2A were most likely to be causal of hearing loss." (PMID 39062005, 2024). "Biallelic variants in USH2A are associated with autosomal recessive Usher syndrome Type II, consistent with the diagnosis reached by clinical evaluation which included progressive retinal degeneration and hearing loss apparent at a young age." (PMID 35346118, 2022). "In addition, non-syndromic RP and non-syndromic hearing loss can be also caused by USH2A variants." (PMID 33105608, 2020). "As regards genotype-phenotype correlation associated with USH2A p.(Cys759Phe) variant, the presence of a p.(Cys759Phe) allele in homozygous state or in combination with other USH2A missense mutation is associated with a RP or a RP with a late onset of hypoacusis clinical subtypes." (PMID 29912909, 2018). "Where USH2A function is severely impaired, [for instance, with biallelic loss of function (LOF) variants], moderate-to-severe early-onset hearing impairment is also present, leading to USH2 (first described by Albrecht von Gräfe in 1858)." (PMID 39120292, 2024). "The clinical features of hearing loss caused by STRC and USH2A gene mutations that are most frequent in the Russian population were presented in our previous papers." (PMID 36555390, 2022). "We further show that Ush2a heterozygote mice have low-level hearing impairments, persistent higher-order acoustic processing deficits and altered vocalizations." (PMID 32313182, 2020). "In contrast, mutations in the USH2 genes, USH2A and GPR98, result in moderate to severe congenital hearing loss, normal vestibular function, and progressive RP." (PMID 19680541, 2009).
hearing loss (continued). "Numerous studies in large cohorts of ethnically different populations have identified pathogenic compound heterozygous or homozygous variants in USH2A as the most frequent cause of isolated recessive RP, without any sign of hearing impairment." (PMID 40149483, 2025). "The predicted lack of usherin function in this model is supported by the early hearing loss phenotype." (PMID 39922978, 2025). "In the non-syndromic form of IRD, “disease-specific” pathogenic variants in the USH2A gene have been described (i.e., alleles associated with retinal degeneration without childhood-onset hearing loss)." (PMID 39596236, 2024). "And other proteins in ECM have also been shown to be involved in hereditary hearing loss, for example, mutated Usherin caused Usher syndrome IIA and mutated collagen XI caused nonsyndromic deafness." (PMID 23936043, 2013). "In the cochlea, usherin protein exists in two isoforms during early stereocilia development, and functional studies in mice have shown that gene knockout results in non-progressive sensorineural hearing loss." (PMID 39596236, 2024). "Our studies show that retinal phenotypes may not be present when hearing loss is first observed in pediatric patients with USH2, even if the patient has two truncated USH2A alleles." (PMID 37981655, 2023). "Subsequently, the USH2A missense variant p.C759F was firstly reported to be associated with ARRP without hearing impairment in 2000, which was presumed to affect the disulfide bridge in the fifth laminin epidermal growth factor-like domain of the USH2A protein." (PMID 36875754, 2023). "Furthermore, the Ush2a−/− hearing phenotype has a later onset at P120 and is restricted to higher frequency when compared to other USH2 mouse lines which exhibit early-onset hearing loss at all frequencies tested." (PMID 37700068, 2023). "Homozygous or compound-heterozygous mutations in the gene encoding usherin (USH2A) on chromosome 1q41 have been implicated in the pathogenesis of non-syndromic retinitis pigmentosa (RP, OMIM 613809) and in Usher Syndrome Type IIA (OMIM 276901) where RP occurs alongside hearing loss." (PMID 35346118, 2022). "In conclusion, truncating USH2A variants were more frequently identified in syndromic USH2A-RP patients who have congenital hearing loss than in non-syndromic USH2A-RP patients without hearing loss." (PMID 33105608, 2020). "Moreover, patients with two truncating USH2A mutations develop significantly more severe hearing impairment throughout life than patients with two non-truncating mutations." (PMID 30948794, 2019). "Similarly, it was reported that USH2 patients carrying the p.Glu767Serfs*21 USH2A mutation can have earlier diagnosis of disease, onset of night blindness, onset of visual field loss, diagnosis of cataract and onset of hearing loss than those carrying the p.Cys759Phe mutation." (PMID 30948794, 2019).